ADAM9 (ADAM metallopeptidase domain 9)
Diseases named in the same sentence as ADAM9 in open-access papers (continued):
Sharing a sentence is not in itself a finding about the gene and the disease.
tumor (continued). "In addition, we observed that expression levels of the ADAM9 protein, but not mRNA, were elevated in individuals with larger tumor sizes (FC = 1.47) and distant metastases (FC = 5.14)." (PMID 40429751, 2025). "More-robust associations between the rs6474526 SNP and advanced clinical T stages were observed in PCa patients without BCR, suggesting that the ADAM9 rs6474526 SNP may influence tumor growth, especially in patients without BCR." (PMID 39628685, 2024). "Hence, miR-126-3p/ADAM9 may be involved in controlling the EMT in LUAD, generally considered a critical mechanism in tumor cell metastasis." (PMID 36171576, 2022). "Besides the targeting of ATP Binding Cassette Subfamily E Member 1 (ABCE1) factor, involved in tumor growth, miR-203 also modulated the oncogene ADAM Metallopeptidase Domain 9 (ADAM9) and long non-coding RNA HULC to inhibit the invasion and migration of cancer cells." (PMID 34069740, 2021). "In addition, impaired MMP7, MMP9, and ADAM9 expression were found in ALOC-EO-treated B16F10 cells in a dose-dependent manner in vitro indicating that ALOC-EO suppresses the expression of tumor cell-derived proteases." (PMID 34360915, 2021). "In addition, through either proteolytic or non-proteolytic pathways, ADAM9 promotes tumor progression, therapeutic resistance, and metastasis of cancers." (PMID 33096780, 2020). "Taken together, whereas the known α-secretase enzymes, mainly ADAM10 and ADAM17 (TACE) and in some degree ADAM9, are involved in APP α-secretase cleavage, they are not APP-specific and cleave various substrates associated with inflammation, tumor formation, and progression." (PMID 29560732, 2018). "Notably, in metastatic lung tumors from TC1-WT group, we found higher expression of ADAM9 was significantly detected in well vascularized tumor nodules compared with tumor nodules without vessels by measuring H scores." (PMID 29118335, 2017). "The metalloprotease domain of ADAM9 can cleave the heparin-binding epidermal growth factor like growth factor (HB-EGF) precursor to yield soluble HB-EGF29, thereby activating epidermal growth factor receptor (EGFR) signal transduction to promote tumor growth and angiogenesis." (PMID 29118335, 2017). "Although dihydrotestosterone modulates the gene expression of ADAM9, ADAM10 and ADAM17 in an androgen-dependent cell line, the expression of the ADAM species in these tumor cell lines may result mainly from the gene regulation associated with transformation of the cells." (PMID 16277668, 2005). "Our findings revealed that rs6474526 variants were significantly associated with larger tumor sizes and distant metastases of LUAD in female and non-smoking groups, suggesting that this ADAM9 SNP may serve as a useful predictor of disease progression in both LUAD populations." (PMID 40429751, 2025). "In line with this, KD of ADAM9 in HCT116 cells drastically reduced phospho-S6K, a signature mTOR target that facilitates tumor invasion including CRC invasion, without affecting total S6K levels." (PMID 35780836, 2022). "ADAM9 and SERPINA1 expression between tumour and tumour adjacent normal tissue were not significantly different (p = .634.491, respectively)." (PMID 34187256, 2021). "Unlike ADAM9, other ADAM family genes ADAM10 and ADAM17 neither differed in their expression levels between HCC tumor tissues and adjacent normal liver tissues, nor showed significant correlation with survival analysis." (PMID 32245188, 2020).
cancer (98 papers, 2008 to 2026). A tumor composed of atypical neoplastic, often pleomorphic cells that invade other tissues. "These SNPs were chosen based on previous reports indicating their association with the risk, severity, or progression of cancers or Alzheimer’s disease, as well as their influence on ADAM9 gene expression." (PMID 40429751, 2025). "From these results, it can be derived that the expression of ADAM9 is associated with the exacerbation of cancer and correlates with the malignancy." (PMID 35740916, 2022). "Alternatively, spliced variants of ADAM12 and ADAM9 were identified in activated hepatic stellate cells and among those of ADAM9, the short form (ADAM9-S) promoted cancer cell invasion." (PMID 33805340, 2021). "In support of these experimental studies, clinical data demonstrated that the expression of ADAM8 and ADAM9 associated with increased metastatic spread and reduced patient survival in a range of cancers." (PMID 26956475, 2016). "ADM-2 is an ortholog of the human ADAM9, which is implicated in inflammation, cancer, and AD by cleaving the APP, but whether ADAM9 plays a potential role in Aβ removal is unknown." (PMID 37728486, 2023). "Indeed, ARHGEF17 was previously reported to be directly involved in mitosis and the expression of ADAM9 was associated with the progression and resistance of several cancer types." (PMID 35251951, 2021). "Most notably, ADAM family members such as ADAM-9,-10,-12,-15 and 28 have been shown to be associated with cancer progression and may serve as molecular targets for cancer therapy." (PMID 28852196, 2017). "Concordant with these observations in other human cancers, we also observed that high ADAM9 mRNA expression was associated with poor clinical outcomes and thus we speculate that it could serve as an independent prognostic factor in LGGs." (PMID 27571068, 2016). "Therefore, ADAM9 causes the degradation of specific substrates, releases active growth factors, and interacts with key regulatory factors, and its expression is related to several cancer processes, including cell growth and invasion." (PMID 35740916, 2022). "Recognizing the critical role of ADAM9 as a protease with oncogenic effects in cancer progression, particularly through EGFR activation in various cancers, including LUAD, we investigated polymorphisms located on promoter and intron regions of the ADAM9 gene." (PMID 40429751, 2025). "Many cancers, including ovarian cancer 37, lung cancer 38, 39, colorectal cancer 40, and stomach cancer 41, have ADAM9 overexpression." (PMID 39898241, 2025). "Next, to examine the effects of ADAM9 genetic polymorphisms on the clinicopathological features of LUAD, factors including primary tumor size, cancer stage, lymph node involvement, cell differentiation, and distant metastasis were assessed." (PMID 40429751, 2025). "ADAM9 is a protein that has a significant impact in processes such as development, inflammation, degenerative diseases, and cancer through proteolytic processing of cell surface proteins and cell adhesion." (PMID 40943358, 2025). "In colorectal cancer, NSD2 overexpression accelerates cell proliferation and migration by increasing global H3K36me2 levels and several cancer-promoting genes, such as ADAM9, EGFR, and MET." (PMID 41301842, 2025). "Recent studies demonstrated a relationship between elevated ADAM9 levels and progression of various cancer cells 17,18." (PMID 39628685, 2024). "Combining agents that target ADAM9 activity with conventional multi-kinase inhibitors presents a promising future therapeutic approach to enhance the effectiveness of cancer management and treatment." (PMID 39346916, 2024). "The combination of agents targeting ADAM9 activity and conventional multi-kinase inhibitors represents a useful future therapeutic strategy to enhance the efficacy of cancer management and treatment." (PMID 36572816, 2023).
cancer (continued). "The treatment of bone marrow and SH-SY5Y cells with the previously developed, unoptimized ADAM9-MSNs resulted in significant non-cancer-specific cell death." (PMID 37445886, 2023). "Another mechanism of platelet activation by cancer cells is mediated by ADAM9 (a disintegrin and metalloproteinase 9), which is found in several cancer types and has been correlated with tumor aggressiveness and poor prognosis." (PMID 36901997, 2023). "TCGA analysis revealed that ADAM9 mRNA expression was significantly higher in stage IV and high-grade cancer than in other stages and low-grade cancer." (PMID 35740916, 2022). "Many other studies have reported that ADAM9 knockdown suppressed migration in cancer cells compared with normal cells." (PMID 35740916, 2022). "In this study, ADAM9 knockdown significantly induced cell-cycle accumulation at G0/G1 phase in T24, and similar results have been observed in other types of cancer." (PMID 35740916, 2022). "In this study, we proved that there is a significant difference in ADAM9 expression level depending on the grade of cancer." (PMID 35740916, 2022). "This study is in accord with other cancer studies but also reports a new finding that the effect of ADAM9 knockdown was more pronounced in muscle-invasive cancer than in non-muscle-invasive cancer." (PMID 35740916, 2022). "Splice variants have been reported for ADAM9 and ADAM12 giving rise to secreted forms with implication in cancer cell invasion." (PMID 33805340, 2021). "In conclusion, we designed an ADAM9-responsive drug delivery system that allows drugs of choice to be delivered to cancer cells." (PMID 34282781, 2021). "Disintegrin and a metalloproteinase (ADAM9), a type I transmembrane protein, are overexpressed in various cancers, including lung cancer." (PMID 34639167, 2021). "This direct regulation of ADAM9 by miRNAs creates a potential niche for development of miRNA-based therapies in cancer treatment." (PMID 32719332, 2020). "Previous studies indicated that ADAM9 activated EGFR-AKT pathway via shedding HB-EGF from cell surface to promote cancer progression." (PMID 32637415, 2020). "The binding sites of these miRNAs are located on 3′-UTR of ADAM9, and lower expression of these miRNAs results in the overexpression of ADAM9 and promotes cancer cell migration and invasion in vitro." (PMID 33096780, 2020). "Recently, several studies demonstrate the necessity of ADAM9 in chemo-resistance in distinct cancer types." (PMID 33096780, 2020). "Mostly expressed by white cells, Adam9 has been reported to get upregulated during many pathological processes including cancers." (PMID 32275707, 2020). "Evidence to date supports the use of ADAM9 as a potential biomarker in inflammatory diseases and as a prognostic marker in cancers." (PMID 33096780, 2020). "Due to the critical roles of ADAM9 in cancer, ADAM9 is targeted by numerous miRNAs to modulate the tumorigenesis." (PMID 33146718, 2020). "In different types of tumors, ADAM9 interacts with different specific integrins to regulate the occurrence and development of malignant tumors." (PMID 32875951, 2020). "ADAM9 was reported to facilitate the cancer progression by mediating ectodomain shedding of HB-EGF and major histocompatibility complex class I-related chain A (MICA)." (PMID 32637415, 2020). "In this review, we summarize the current understanding of ADAM9 in biological function, pathophysiological diseases, and various cancers." (PMID 33096780, 2020). "The normal molecular mass of ADAM9 is 124 and 84 kDa.Compared with normal breast tissue, 84 kDa length protein is detected more frequently in primary cancer." (PMID 32875951, 2020). "Accumulating evidence has demonstrated the overexpression of ADAM9 in cancers and promoted the cancer progression." (PMID 33146718, 2020). "After fully understanding therelated functions of ADAM9 in cancer, the next step should focus on how to specifically regulate it." (PMID 32875951, 2020).
cancer (continued). "Previous studies indicated that ADAM9 mediates cancer progression via regulating epithelial-to-mesenchymal transition (EMT), shedding EGFR ligands, and activating EGFR/AKT signaling pathway." (PMID 32637415, 2020). "Previously, enhanced ADAM9 expression has been shown to promote cancer progression by increasing cancer cells motility, invasion, and proliferation." (PMID 32637415, 2020). "Sprout formation of human umbilical vein endothelial cells (HUVECs) is promoted by ADAM9, as examined by transfer of cancer cell conditioned medium; this finding further supports a pro‐angiogenic role of ADAM9 expressed by PDAC cancer cells." (PMID 30556643, 2019). "Further, MiR-126 was found to target ADAM9 (disintegrin and metalloproteinase domain-containing protein 9), which is highly expressed in cancer." (PMID 31850200, 2019). "Immunoblotting analysis of cancer cell conditioned medium highlighted that ADAM9 regulates the levels of angiogenic factors, including shed heparin‐binding EGF‐like growth factor (HB‐EGF)." (PMID 30556643, 2019). "This supports findings from previous reports that emphasize a pro‐angiogenic function of ADAM9 in cancer." (PMID 30556643, 2019). "Other factors that have already been mentioned in terms of their role in the EMT process but also contribute to angiogenesis in various cancers are ADAM9 and FGF18." (PMID 31641356, 2019). "Several ADAM family members, particularly ADAM9, ADAM10, ADAM12, ADAM15 and ADAM17, have been implicated in cancer formation and progression." (PMID 30081852, 2018). "ADAM9 is expressed in endothelial cells and has been shown to play a role in neovascularisation both in retinal development and in pathologies such as cancer." (PMID 28928095, 2017). "Here, we showed that ADAM9 also contributes the functions of angiogenesis and vascular remodeling for cancer progression through regulation of VEGFA, ANGPT2, and PLAT via in vitro and in vivo experiments." (PMID 29118335, 2017). "Our previous study has demonstrated that ADAM9 enhances cancer cells’ ability to survive in the blood and promotes metastasis by a plasminogen activator-based pathway in activating the anoikis-resistant gene CDCP114." (PMID 29118335, 2017). "Accumulating evidence has demonstrated that overexpression of a disintegrin and metalloproteinase 9 (ADAM9) promotes cancer cell metastasis." (PMID 29118335, 2017). "The A disintegrin and metalloproteinase 9 (ADAM9) protein has been suggested to promote carcinoma invasion and appears to be overexpressed in various human cancers." (PMID 27571068, 2016). "ADAM9, a member of this family, has been suggested to promote carcinoma invasion, and seems to be markedly up-regulated in many human cancers." (PMID 27571068, 2016). "ADAM9 is consistently overexpressed in various human cancers, and has been shown to play an important role in tumorigenesis." (PMID 27990250, 2015). "Diffuse staining for RCAS1 and ADAM9 was observed both in the cytoplasm and on the cell membrane of cancer cells." (PMID 25177692, 2014). "The precise understanding of the exact role played by RCAS1 and ADAM9 in cancer appears to be of particular importance from the perspective of designing new therapeutic strategies that are based on the control or inhibition of these proteins." (PMID 25177692, 2014). "A precise understanding of the role played by RCAS1 and ADAM9 is essential to design novel strategies to treat cancer." (PMID 25177692, 2014). "Serum RCAS1 levels significantly increased in a manner that was dependent on RCAS1 and ADAM9 expression in both cancer types." (PMID 25177692, 2014). "The expression of several cancer metastasis-related genes such as ADAM9, CDH9 and CD44 was increased following miR-182 knockdown." (PMID 24519909, 2014). "ADAM9 is a secreted protein and its soluble form promoted the invasive phenotype of carcinoma cell lines by binding to the α6β4 and α2β1 integrins on the surface of carcinoma cells through its disintegrin domain." (PMID 25177692, 2014).
cancer (continued). "In conclusion, the findings presented here thus establish that ADAM9 is essential for cancer progression during the transition to malignancy." (PMID 23342005, 2013). "Looking for downstream target genes, we demonstrate miR-126&126* capabilities to directly regulate a disintegrin and metalloprotease domain 9 (ADAM9) and metalloprotease 7 (MMP7), whose aberrant expressions have been associated with a wide variety of cancers." (PMID 23437250, 2013). "At least in the case of ADAM9, this may be induced by an inter-cellular interaction that stimulates the pathway in an adjacent stromal cell (“by-stander effect”); stromal fibroblasts are often intimately associated with cancer cells and can form tight junctions and paracrine interactions with them." (PMID 22570691, 2012). "The normalized ADAM9 expression was significantly higher in cancer than in normal tissue samples (mean change fold 2.7, range: 0.9–12.6; p < 0.0001)." (PMID 18582378, 2008). "Among them, ADAM9, a zinc-dependent metalloproteinases widely overexpressed in various cancers." (PMID 41383622, 2025). "ADAM9, a member of the A disintegrin and metalloproteinase (ADAM) family, facilitates the release of growth factors and was implicated in activating the EGFR-mediated progression in several cancer types." (PMID 40429751, 2025). "As a member of the ADAMs family, ADAM9 is deemed a potential target for treating cancer." (PMID 39898241, 2025). "Several previous studies have shown that ADAM9 is overexpressed in various types of cancer." (PMID 39441449, 2024). "Furthermore, quantitative real-time polymerase chain reaction (qRT-PCR) and immunohistochemistry (IHC) were utilised to determine the differential level of ADAM9 in cancer and para-carcinoma tissues in patients’ samples." (PMID 37082201, 2023). "Identifying novel ADAM9 inhibitors from cell-based assays may encourage the design of more selective compounds that help to block ADAM9-induced promotion of cancer." (PMID 36778124, 2023). "Several previous studies have investigated the relationship between ADAM9 and cancer proliferation." (PMID 35740916, 2022). "Other studies have also found that ADAM9 and microRNA-126, which have been reported to upregulate ADAM9, may be new therapeutic targets and markers for cancer." (PMID 35740916, 2022). "Additionally, from TCGA and GEO study, we found that ADAM9 expression was higher in high-grade cancers." (PMID 35740916, 2022). "Interestingly, ADAM9 is highly expressed relative to other proteases in most cell types, confirming that ADAM9 expression is indeed upregulated in many cancers." (PMID 34282781, 2021). "In general, the results of the bioinformatics analyses implicated that ADAM9, MTHFD2, RRM2, and SLC2A1 are overexpressed in tumors and that the cumulative effect of their overexpression is associated with poor outcomes in multiple types of cancer." (PMID 33664854, 2021). "The expression of ADAM9 in cancer cells can be modulated via certain factors." (PMID 34528498, 2021). "Furthermore, ADAM9 is upregulated by aberrant KRAS/NF-kB signaling in cancer cells, and knocking down ADAM9 suppresses KRAS and MEK-ERK signaling." (PMID 33648511, 2021). "ADAM9 overexpression has been reported in several cancer types, suggesting that the ADAM9-MSN delivery system may hold promise in other malignancies as well." (PMID 34282781, 2021). "ADAM9, a metallozinc proteinase expressed on the cell surface, predicted dismal prognostic parameters as well as short survival times in patients with various cancers." (PMID 34528498, 2021). "It is reported that ADAM9 facilitates the cancer cell survival and metastasis." (PMID 33146718, 2020). "Moreover, currently used therapeutic agents (such as sorafenib and regorafenib) work by reducing ADAM9 levels to enhance cancer treatment." (PMID 33096780, 2020). "Therefore, comprehensively understanding the mechanism of ADAM9 is crucial for the development of therapeutic anti-cancer strategies." (PMID 33096780, 2020).